IL25 (interleukin 25)
Diseases named in the same sentence as IL25 in open-access papers (continued):
Sharing a sentence is not in itself a finding about the gene and the disease.
endometriosis (4 papers, 2020 to 2024). The growth of functional endometrial tissue in anatomic sites outside the uterine body. "Th2 cells and MCs express IL-25, which is increased in the PF of patients with endometriosis." (PMID 32145751, 2020). "The levels of IL-25 and IL-17α are also elevated in women with endometriosis." (PMID 32145751, 2020). "Unfortunately, there is limited specific information regarding the sensitivity and specificity of IL-25 and TSLP in diagnosing endometriosis." (PMID 39767772, 2024). "There is currently no reliable information available on the influence of IL25 and TSLP gene polymorphisms on cytokine levels in endometriosis." (PMID 39767772, 2024). "One study found higher IL-25 levels in the peritoneal fluid of endometriosis patients, though these levels did not correlate with disease stage." (PMID 39767772, 2024).
fungal infections (4 papers, 2019 to 2024). "Interleukin-17 (IL-17) A and IL-17F cytokines, which are members of the IL-17 family along with IL-17B, IL-17C, IL-17D and IL-17E/IL-25, play a central role in host defense against bacterial and fungal infections as well as in tissue repair." (PMID 33833999, 2021). "IL-17E (IL-25), which potentiates allergic inflammation, mediates a strong host defense during parasitic and fungal infection." (PMID 31244826, 2019).
lung diseases (4 papers, 2017 to 2025). "Third, considering the redundant nature of cytokines, future studies should focus on whether combined targeting of IL‐25/IL‐33/TSLP is necessary to completely block the progressive fibrotic lung diseases." (PMID 36082495, 2022). "For example, gut microbial dysbiosis has been implicated in the pathogenesis of lung diseases through various immune-mediated pathways, including modulation of T helper 17 cell (Th17) responses, CD8 T-cell activity, and interleukin-13 (IL-13), interleukin 25 (IL-25), and prostaglandin E2 production." (PMID 40378019, 2025).
lupus (4 papers, 2019 to 2023). "Involvement of IL-25 and its role in stimulating Th2 cytokines in SLE and SLE-associated lupus nephritis remains obscure." (PMID 31697750, 2019). "Although IL-25 may be involved in disease progression in SLE patients, high level of IL-25 in lupus mice acts a protective effect on disease progression." (PMID 37005677, 2023). "Several studies reported that the serum level of IL-25 was higher in patients with SLE, especially in patients with lupus nephritis." (PMID 37005677, 2023). "Administration of IL-25 relieved SLE symptoms in lupus-prone MRL/lpr mice, including the decline of anti-dsDNA and IgG, and the degree of kidney damage was also reduced." (PMID 37005677, 2023). "Both reports claim IL-25 expression is increased in the serum of SLE patients, especially in patients with active disease severity and lupus nephritis." (PMID 35444658, 2022). "IL-9 and IL-10 showed a significant positive correlation with IL-25 in all 17 SLE patients with lupus nephritis, whereas a significant negative correlation was observed with IL-5 and IL-6." (PMID 31697750, 2019). "Although IL-25 is upregulated in SLE patients, IL-25 can ameliorate lupus pathogenesis in mice by inhibiting inflammatory cytokines." (PMID 34122457, 2021). "Several studies show that IL-25, together with other Th2-related cytokines, is significantly increased in SLE patients, especially in those with lupus nephritis, contributing to the pathogenesis of SLE." (PMID 34122457, 2021). "Hence, this study was undertaken to examine the association of IL-25 and Th2 cytokines in SLE patients with and without lupus nephritis (LN) involvement among Malaysian Malay female patients." (PMID 31697750, 2019). "Thus, the aim of this research is to determine the plasma levels of IL-25 and Th2-associated cytokines (IL-4, IL-5, IL-6, IL-9, IL-10, IL-13) in SLE patients with (SLE-LN) and without lupus nephritis." (PMID 31697750, 2019). "IL-10 showed a significant positive correlation with IL-25 in all 47 SLE patients without lupus nephritis, whereas a significant negative correlation was observed with IL-5." (PMID 31697750, 2019). "IL-9 and IL-10 showed a significant positive correlation with IL-25 in 64 patients of SLE with and without lupus nephritis." (PMID 31697750, 2019).
melanoma (4 papers, 2016 to 2024). A malignant, usually aggressive tumor composed of atypical, neoplastic melanocytes. "Further investigation has indicated that Virulizin® stimulates IL‐25 production predominantly from B cells, resulting in elevated blood eosinophilia and infiltration of activated eosinophils to the melanoma microenvironment." (PMID 34128588, 2021). "IL-25 injections in human tumor xenograft models including melanoma, breast, lung, colon, and pancreatic cancers were shown to have antitumor efficacy with increased eosinophils in the peripheral blood of these mice." (PMID 27165713, 2016). "Our data demonstrate that tissue specialization of IL-25-responsive tumor-promoting intestinal ILC2s have opposite functions to the tissue-specific IL-33-activated ILC2s that are protective in orthotopic pancreatic cancer and melanoma." (PMID 35658010, 2022). "IL‐25 is produced not only by immune cells (e.g., T cells, DCs, and macrophages) but also other non‐immune cells (e.g., fibroblasts, epithelial cells, keratinocytes) and even some cancer cells (such as melanoma, liver, breast, and cervical cancers)." (PMID 34128588, 2021).
ulcerative colitis (4 papers, 2012 to 2025). An inflammatory bowel disease involving the mucosal surface of the large intestine and rectum. "For instance, IL‐25 and IL‐25R expression in inflammatory conditions such as bladder polyp or ulcerative colitis are increased compared to bladder cancer or CRC, respectively." (PMID 34128588, 2021).
adenoma (3 papers, 2022 to 2023). A neoplasm arising from the epithelium. "Therapeutic antibody-mediated blockade of IL-25-signalling decreased intratumoral ILC2s, MDSCs and adenoma/adenocarcinoma, while increasing anti-tumor adaptive T cell and IFNγ-mediated immunity." (PMID 35658010, 2022).
alopecia areata (3 papers, 2021 to 2025). Loss of scalp and body hair involving microscopically inflammatory patchy areas. "It found that people with alopecia areata had increased plasma levels of the Type 2 cytokines IL-33, IL-31 and IL-17E (IL-25), in addition to the Type 17 cytokines IL-17A, IL-21, IL-23 and IL-17F." (PMID 38892934, 2024).
atopic asthma (3 papers, 2021 to 2023). An asthma that is characterized by symptoms that are triggered by an allergic reaction caused by inhaled allergens such as dust mite allergen, pet dander, pollen and mold. "In atopic asthma, allergens release proteases, which disrupt the epithelial barrier and induce secretion of alarmins such as interleukin-25 (IL-25), interleukin-33 (IL-33), and thymic stromal lymphopoietin (TSLP) from epithelial cells." (PMID 38352244, 2023). "An increased expression of IL-17E (IL-25) has been observed in the bronchial mucosa and patients with atopic asthma after allergen challenge and its levels in sputum correlate with disease severity." (PMID 35883573, 2022).
bladder cancer (3 papers, 2016 to 2023). "However, the underlying mechanism involved in the contribution of IL‐25 and IL‐25R in colorectal and bladder cancer regression has not yet been defined." (PMID 34128588, 2021).
Crohn disease (3 papers, 2022 to 2025). A gastrointestinal disorder characterized by chronic inflammation involving all layers of the intestinal wall, noncaseating granulomas affecting the intestinal wall and regional lymph nodes, and transmural fibrosis. "Ileal biopsies showed that clinically overt Crohn’s disease was associated with expansion of IL-25/IL-17E-producing tuft cells and ILC2s compared to pre-IL-17i treatment levels." (PMID 36672830, 2022). "Furthermore, IL-17i-related Crohn’s disease is associated with overexpression of IL-25/IL-17E-producing tuft cells and ILC2s." (PMID 36672830, 2022). "Then, ileal biopsies obtained from SpA patients who developed clinically overt Crohn’s disease after treatment with IL-17i (n = 5) were analyzed for expression of IL-23/Th-17 related cytokines, IL-25/IL-17E-producing cells and type-2 innate lymphoid cells (ILC2s)." (PMID 36672830, 2022).
eczema (3 papers, 2018 to 2024). "We used single factor analysis to evaluate the statistically significant or near significant variables (history of eczema, systemic glucocorticoid treatment, moderate to severe condition, IL-25)." (PMID 33691633, 2021). "Considering we cannot confirm whether the P3 case has an IL25 or NLRP8 variant which could play a role in the absence of eczema or M. contagiosum, it would be difficult to determine whether these variants are playing a role in the proband." (PMID 29556235, 2018).
Hepatitis (3 papers, 2019 to 2024). Inflammation of the liver. "We previously found that GL can alleviate Con A-induced hepatitis by regulating the expression of IL-25 in the liver." (PMID 38785317, 2024). "In our previous study, we reported that GL alleviates Con A induced hepatitis by reducing the production of IL-17 and enhancing the expression of IL-25." (PMID 38785317, 2024). "In our previous study, we found that GL can alleviate hepatitis by reducing IL-17 and promoting the expression of IL-25, which is known for promoting the type 2 immune responses." (PMID 38785317, 2024). "Our previously study has suggested that Tpl2 critically regulate IL-17A-induced signaling in astrocytes to mediate autoimmune inflammation, here we also demonstrated that Tpl2 is a key modulator in IL-25-induced signaling in hepatocyte to restrain hepatitis." (PMID 31481966, 2019).
influenza infection (3 papers, 2021 to 2025). "IL-25, an alarmin released by stressed upper epithelial cells, was also significantly increased post infection, although prior evidence for IL-25 production by ATIIs during influenza infection remains limited." (PMID 41502560, 2025).
liver cancer (3 papers, 2022 to 2024). An epithelial or non-epithelial malignant neoplasm that arises from the liver. "In contrast with current findings, the serum level of IL-25 has been shown to increase in patients suffering from hepatic cancer (HCC) as compared with CHC." (PMID 35056005, 2022). "This study suggests that serum IL-25 levels may be an independent and useful tumor marker for the diagnosis of liver cancer." (PMID 36119529, 2022). "It indicated that IL-25 might be a potential tumor marker for the diagnosis of liver cancer." (PMID 38818476, 2024).
pneumonia (3 papers, 2021 to 2024). An acute, acute and chronic, or chronic inflammation focally or diffusely affecting the lung parenchyma, caused by an infection in one or both of the lungs (by bacteria, viruses, fungi, or mycoplasma.). "We found that high levels of IL-6, IFN-γ, and IL-2 and low levels of IL-5, IL-25, IL-17A, and IL-22 were found in the severe pneumonia group compared to the nonsevere pneumonia group." (PMID 34692846, 2021).
Trichinella spiralis infection (3 papers, 2016 to 2023). "During Trichinella spiralis infection, worm expulsion accompanied IL-25 mediated host protection and IL-25 induces angiogenin-4 expression." (PMID 27089535, 2016). "Therefore, IL-25 can affect airway diseases and Trichinella spiralis infection through IL-9." (PMID 37005677, 2023). "Following Trichinella spiralis infection, mice treated with IL-25-neutralizing antibodies failed to effectively expel T. spiralis." (PMID 37005677, 2023).
type 1 diabetes (3 papers, 2021 to 2024). "However, IL-25, as an IL-17 cytokine family member, exhibits an inhibitory effect on the pathogenesis of type 1 diabetes." (PMID 34122457, 2021).
airway allergy (2 papers, 2015 to 2024). "Interestingly, IL-25 is a key component in airway hypersensitivity, and antibody blockade of IL-25 in airway allergy was found to be most complete during the effector, rather than sensitization, phase." (PMID 25816012, 2015).
amebiasis (2 papers, 2017 to 2021). A parasitic infectious disorder caused by amoebas. "We expected that IL-25-mediated protection in amebiasis would be associated with a shift from a proinflammatory response to type 2 immunity." (PMID 28246365, 2017). "In order to describe the immune response induced by IL-25 during amebiasis, we measured IL-4, IL-5, and IL-9 by enzyme-linked immunosorbent assay (ELISA) from cecal tissue lysates of mice after E. histolytica challenge with or without rIL-25 treatment." (PMID 28246365, 2017). "It is likely that tuft cells also play an important role in amebiasis since they produce IL-25, which has been found to be protective." (PMID 33502317, 2021). "Further investigation is required to understand the cellular and molecular mechanism of the IL-25–eosinophil pathway during amebiasis." (PMID 28246365, 2017). "We concluded that IL-25 provides protection from amebiasis, which is dependent upon intestinal eosinophils and suppression of TNF-α." (PMID 28246365, 2017). "From these results, we hypothesized that suppression of TNF-α expression was a possible mechanism by which IL-25 mediates protection against amebiasis." (PMID 28246365, 2017). "In order to test whether IL-25 would protect mice against amebiasis, we injected into the peritoneum 0.5 μg of rIL-25 or phosphate-buffered saline (PBS) daily for 4 days prior to and 4 days after E. histolytica challenge." (PMID 28246365, 2017). "The hypothesis that IL-25 acts to protect from amebiasis through eosinophil conversion of type 1 to type 2 macrophages therefore remains to be tested." (PMID 28246365, 2017).
bullous pemphigoid (2 papers, 2024 to 2025). Bullous pemphigoid (BP) is the most common form of autoimmune bullous dermatosis. "In this study, we aim to explore the relationship between serum levels of IL-17, IL-22, IL-25, EOS in peripheral blood, anti-BP180 antibodies, anti-BP230 antibodies, and IgE and disease activity and severity in patients with bullous pemphigoid." (PMID 40800128, 2025).
cervical cancer (2 papers, 2018 to 2021). A primary or metastatic malignant neoplasm involving the cervix. "This agent remarkably downregulates expression of IL‐25 and IL‐25R and reverses the regulatory effects of rIL‐25 on viability, migration, and invasion of cervical cancer cells." (PMID 34128588, 2021). "Hence, cisplatin might be effective for treating cervical cancer patients with upregulated IL‐25 expression." (PMID 34128588, 2021).
chronic kidney disease (2 papers, 2017 to 2021). Impairment of the renal function secondary to chronic kidney damage persisting for three or more months. "An initial study evaluating therapeutic IL-25 was undertaken in a model of chronic kidney disease (CKD), in which doxorubicin administration causes focal segmental glomerular sclerosis-like disease." (PMID 33749662, 2021).
Chronic spontaneous urticaria (2 papers, 2022 to 2024). "Chronic spontaneous urticaria is characterized by increased levels of IL-25, IL-33, and TSLP, indicating the possible involvement of ILC2s." (PMID 38474426, 2024). "IL-25 and IL-33 can modulate many aspects of mast cell function, including proliferation and production of a variety of Th2 cytokines in chronic spontaneous urticaria." (PMID 35874756, 2022). "In addition, increased expression of IL-25 and IL-33 on mast cells was observed in lesional skin of patients with chronic spontaneous urticaria." (PMID 35874756, 2022).
colon cancer (2 papers, 2016 to 2022). "It is unknown what effect IL-25 has on tumor-associated gene expression levels during colonic tumor development." (PMID 27165713, 2016). "Taken together these data suggest that IL-25 plays an inhibitory role in the growth and development of colonic tumors." (PMID 27165713, 2016). "We have examined the role of IL-25 in an inflammation-induced colon cancer model using both antibody blockade of the cytokine and genetic deletion of signaling via IL-25 knock-out mice." (PMID 27165713, 2016). "The unexpected effect of IL-25 blockade resulting in an increase in grossly evident colonic tumors led to the hypothesis that a genetic deletion of IL-25 would also reveal an increase in tumor development." (PMID 27165713, 2016). "In Summary, due to the known role for IL-25 to augment disease pathogenesis in UC and because UC often progresses into colon cancer, an AOM/DSS-induced murine model of colon carcinogenesis was used to establish the role for IL-25 in this environment." (PMID 27165713, 2016).
contact dermatitis (2 papers, 2018 to 2023). An inflammatory skin condition caused by direct contact between the skin and either an irritating substance or an allergen. "Additionally, patients with contact dermatitis have also been observed to exhibit a significant increase in IL-25 expression, which could promote the production of associated inflammatory factors (e.g., IL-5 and IL-13), which in turn led to local inflammation." (PMID 37005677, 2023). "In contact dermatitis, IL-1β produced from skin dendritic cells could promote the activation of Th17 cells by IL-25, resulting in an increased level of IL-17 A expression, which in turn, induced the local inflammation." (PMID 37005677, 2023).
coronary artery disease (2 papers, 2024 to 2025). "Among the inflammatory markers studied, the authors identified IL-25 and MHR as stronger markers for assessing the severity of coronary artery disease; however, in our opinion, the main limitation of the presented results is the size of the study group." (PMID 39518736, 2024).
cryptococcosis (2 papers, 2023). An acute or chronic, localized or disseminated infection by Cryptococcus neoformans. "Although IL-25 was found to exacerbate the pathogenesis of cryptococcosis, how IL-25 participates with IL-33 in regulating Th2-type immune responses during C. neoformans infections remains unclear." (PMID 37337050, 2023). "In this study, authors highlighted the role of TH2 cells in IL-25 signaling, but a group of ILC2-like cells also has high expression of IL-17RB during cryptococcosis." (PMID 37703276, 2023).
depression (2 papers, 2020 to 2024). "IL-17, a pro-inflammatory cytokine, is a member of the cytokine family comprising IL-17A, IL-17B, IL-17C, IL-17D, IL-17E (IL-25) and IL-17F and it was found before, to be elevated in the serum of patients suffering from depression." (PMID 33322667, 2020).
enteroviral infection (2 papers, 2024 to 2025). "Mechanically, trained tuft cells produced more IL-25, which suppressed enteroviral infections via SAT1-mediated intracellular polyamine deficiency." (PMID 39261649, 2024). "Our present study implies that intestinal tuft cells can be trained by IL-25 and it may explain the different susceptibility in enteroviral infections between adults and children from an immune training perspective." (PMID 39261649, 2024). "Given that IL-25 can be induced by multiple gut microbes during human growth and development, including shifts in gut flora abundance, which may partially explain the different susceptibility to enteroviral infections between adults and children." (PMID 39261649, 2024). "The authors showed that tuft cells can be trained by IL-25, which supports faster and higher levels of IL-25 production in response to enteroviral infection and further exhibits an anti-enteroviral effect." (PMID 40231720, 2025). "In short, we speculated that IL-25-trained tuft cells in infancy supported more IL-25 production to fight with enteroviral infections." (PMID 39261649, 2024). "Possibly, this IL-25-mediated tuft cell training effects not only protect the host from enteroviral infections in adults, but also extend protection against unrelated pathogens with marked age-susceptibility differences, which requires more research to confirm in the future." (PMID 39261649, 2024).